SLC39A8 (solute carrier family 39 member 8)
Diseases named in the same sentence as SLC39A8 in open-access papers (continued):
Sharing a sentence is not in itself a finding about the gene and the disease.
cancer (24 papers, 2012 to 2025). A tumor composed of atypical neoplastic, often pleomorphic cells that invade other tissues. "The analysis revealed that the mutation frequencies of SLC39A1, SLC39A4, and SLC39A8 in pan-cancer patients were 4%, 6%, and 0.9%, respectively." (PMID 38230214, 2024). "Recently, abnormal SLC39A8 expression has been reported to increase cancer risk and impact the clinical outcomes of several cancers, partly through ferroptosis-related mechanisms." (PMID 38022516, 2023). "To gain further insights into the biological functions of SLC39A1, SLC39A4, and SLC39A8 in cancers, we utilized the LinkedOmics database to analyze their co-expression profiles in LIHC, CESC/PAAD, and KIRP, respectively." (PMID 38230214, 2024). "The GSE39582 dataset demonstrated a significant difference (P<0.05) in the expression of SLC39A8 between patients in early and late stages of cancer." (PMID 39006076, 2024). "To investigate the associations between the expression of SLC39A1, SLC39A4, and SLC39A8 and immune infiltration in related cancers, we utilized the TIMER database." (PMID 38230214, 2024). "Expression levels of the ferroptosis-related genes GCLC, MAP1LC3A, SLC7A11, and SLC39A8 in NAT10 KD cancer cells were significantly downregulated, therefore validating the results from our RNA-seq data." (PMID 37237981, 2023). "Our results showed significant downregulation in expression of essential genes related to ferroptosis, namely SLC7A11, GCLC, MAP1LC3A, and SLC39A8 in NAT10-depleted cancer cells." (PMID 37237981, 2023). "We have previously shown that upregulated ZIP8 (SLC39A8) gene expression was common across multiple cancer types." (PMID 36330220, 2022). "For patients with LUAD, mRNA levels of SLC39A1, 3, 4, 5, 6, 7, 9, 10, 11 and 14 were significant higher in cancer tissues than in relative normal samples, but SLC39A8 and SLC39A12 were expressed lower in cancer samples." (PMID 33535184, 2021). "SLC39A8 protein was mainly located in the plasma membrane of renal tubular epithelial cells from paracancer tissues and cancer cells, the SLC39A8 expression in ccRCC tissues was significantly down-regulated." (PMID 33869056, 2021). "Overall, the findings suggest that the expression of SLC39A8 may be a useful predictor of cancer progression, particularly in relation to N-stage evaluation." (PMID 39006076, 2024). "In light of the aberrant expression and significant roles played by SLC39A1, SLC39A4, and SLC39A8 genes in specific cancers, as well as the link between genetic alterations and cancer development, we further investigated the genetic alterations of these genes using the cBioPortal database." (PMID 38230214, 2024). "Additionally, genetic alteration of SLC39A8 was closely correlated with OS in cancer patients (p-value: 0.0298)." (PMID 38230214, 2024). "Consistently, it has been mentioned that SLC39A8, due to its capability to transport selenium, has the potential to enhance the effectiveness of anti-cancer drugs and could serve as a novel target for cancer treatment." (PMID 39006076, 2024). "Furthermore, by utilizing clinical datasets of 40 different types of cancers from The Cancer Genome Atlas (TCGA) database, we showed that SLC39A8 gene expressions tend to be upregulated in a great number of tumor types." (PMID 36330220, 2022). "Additionally, immune infiltration analysis revealed that SLC39A1, SLC39A4, and SLC39A8 may function as immune regulators in cancers." (PMID 38230214, 2024). "Furthermore, we found that the gene SLC39A8 exhibited the lowest mutation frequency in KIRP, whereas mutations in SLC39A4 were found to significantly impact overall survival (OS), disease-free (DF), and progress-free survival (PFS) in cancer patients, particularly in those with PAAD." (PMID 38230214, 2024). "SLC39A4, 7, 10, 11 and 14 in cancer tissues were significantly highly expressed compared with in normal tissues.(P<0.05) But, expression of SLC39A6 and SLC39A8 were higher in normal samples than in cancer samples." (PMID 33535184, 2021).
cancer (continued). "In a scRNA-seq study involving 10 pairs of human cancer and adjacent normal tissue, a distinct subset of TAMs characterized by high expression of metallothionein family genes, particularly zinc transporter genes SLC30A1 (ZNT-1) and SLC39A8 (ZIP-8), was identified." (PMID 37746302, 2023). "Regrettably, cancer-related studies of the other few candidate genes, including BCS1L, COQ2, and SLC39A8, are still absent, and we will seriously consider deeper research in our future studies." (PMID 36185199, 2022).
tumor (22 papers, 2012 to 2025). "In tumor samples, decreased expression of SLC39A8 is associated with advanced stage and poor prognosis." (PMID 41583444, 2025). "Genome-wide, SLC39A8 (p<4.3×10−10) was one of only 19 genes that passed a combined highly significant statistical association (p<10−9) with tumor aggressiveness." (PMID 23516545, 2013). "SLC39A8 was highly expressed in tumor tissues with strong intensity, while moderate expression was observed in normal tissues." (PMID 40959429, 2025). "At the same time, the correlation of the SLC48A1 and SLC39A8 genes with tumor-infiltrating immune cells was analyzed." (PMID 35118074, 2021). "SLC39A8 has been reported as an important membrane transporter in iron metabolism, differentially expressed in colons, and was associated in CRC tumor aggressiveness." (PMID 34249766, 2021). "IHC was used to further verify the clinical samples, which showed high SLC39A8 levels in tumor tissues." (PMID 35118074, 2021). "The Oncomine database reported an increase in the mRNA expression level of other SLC39 family genes in the tumor tissues compared to the normal control group, except for SLC39A8." (PMID 34925450, 2021). "The interval contains another positional candidate Slc39a8 that is differentially expressed in A vs B6 colons, and that has recently been associated in CRC tumor aggressiveness in humans." (PMID 23516545, 2013). "SLC30A4 and SLC39A8 act as tumor suppressors in a context-dependent manner." (PMID 41583444, 2025). "Similarly, DHCR7 (cholesterol biosynthesis), DDIT4 (mTOR regulation under stress), HNRNPAB (RNA splicing), and SLC39A8 (zinc signaling) all reflect well-documented mechanisms of tumor growth or adaptation." (PMID 40941703, 2025). "Among these significant genes of IL-4 signaling are CFLAR, ALOX5, PMAIP1, EGR1, NCF2, SLC39A8, and PEG10 which have been reported to be associated with tumor progression or chemotherapy-drug resistance through effecting proliferation and apoptosis in previous studies." (PMID 33506057, 2021). "Through bioinformatics analysis of tumor databases, SLC39A8 was identified as a key gene of ZIP family in ccRCC, which could be used as an effective indicator for diagnosing ccRCC and judging its prognosis." (PMID 33869056, 2021). "This contradiction could be clearly explained by the following analysis, that is, the expression of SLC39A8 is slightly up-regulated in early tumors, but with the increase of tumor grade, its expression level decreased gradually." (PMID 33869056, 2021). "With the progression of tumor, the expression of SLC39A8 decreased progressively." (PMID 33869056, 2021). "Furthermore, we showed that ABCC4, DAG1, and SLC39A8 proteins are significantly downregulated in tumors compared to NATs, suggesting that they may play the role of tumor suppressors." (PMID 36499305, 2022). "Specifically, PDSS2, GRSF1, SLC39A8 and P4HA1 were significantly upregulated in tumor tissues compared to normal samples." (PMID 40959429, 2025). "Specifically, analysis of proteomic data from the Human Protein Atlas (HPA) revealed that PDSS2, GRSF1, SLC39A8, and P4HA1 are markedly upregulated in tumor tissues compared to normal samples." (PMID 40959429, 2025). "The identified potential tumor suppressor genes included DAG1, SLC39A8, TMEM173/STING1, RDX, TJP1, CTNNB1, and SMC3." (PMID 36499305, 2022). "Moreover, the expression of GDI1 was up-regulated in tumor samples, whereas GPX3 and SLC39A8 were down-regulated in tumor samples." (PMID 39006076, 2024). "To date, the literature supports the tumor suppressor functions of DAG1, SLC39A8, TMEM173/STING1, TJP1, CTNNB1, and SMC3, but not RDX." (PMID 36499305, 2022).
infection (12 papers, 2016 to 2026). The state of being infected such as from the introduction of a foreign agent such as serum, vaccine, antigenic substance or organism. "Zinc transporter ZIP8 (SLC39A8) is a transcriptional target of NF-κB and an important response to cytokines, bacteria, and infection." (PMID 31546724, 2019).
bacterial infection (4 papers, 2017 to 2024). "In addition, a frequently occurring ZIP8 defective variant (SLC39A8 rs13107325) is strongly associated with inflammation-based disorders and bacterial infection." (PMID 37242309, 2023).
infectious disease (4 papers, 2013 to 2026). A disorder directly resulting from the presence and activity of a microbial, viral, or parasitic agent in humans. "These links to infectious disease outcomes and to inflammatory pathways suggest that SLC39A8 may regulate macrophage antimicrobial pathways, although this awaits functional evidence." (PMID 23738776, 2013).
cardiac disease (2 papers, 2012 to 2019). "In conclusion, SLC39A8-associated kidney function is intimately interconnected with cardiac disease." (PMID 31521203, 2019). "In Slc39a8(neo/neo) liver, angiotensin-1-converting enzyme-2 (Ace2) was also upregulated, perhaps helping to explain the potential clinical role of SLC39A8 in heart disease." (PMID 31521203, 2019).
genetic disorder (2 papers, 2021 to 2023). "The underrepresentation of deleterious SLC39A8 mutations had also been observed in 60,706 subjects from the Exome Aggregation Consortium, which was consistent with pathogenicity of ZIP8 mutations leading to a genetic disorder with a recessive inheritance pattern." (PMID 33790950, 2021).
musculoskeletal disorders (2 papers, 2024 to 2025). "The associations between digestive and musculoskeletal disorders and rs13107325 (manganese), which alters the metal ion transporter ZIP8 (encoded by SLC39A8), could potentially highlight the role of manganese or other divalent trace metals in these conditions." (PMID 38594418, 2024).
skin disorder (1 paper, 2019). Any deviation from the normal structure or function of the skin or subcutaneous tissue that is manifested by a characteristic set of symptoms and signs. "Our study revealed very high frequencies (up to 95%) of chestnut horses harboring NFKB1, SLC39A8, BANK1 and UVSSA in ROH islands, and indicated evidence that these genes may be involved in the reported higher susceptibility of chestnut horses for skin disorders." (PMID 31261764, 2019).
SLC39A8 also shares sentences with these, for which no sentence is quoted: cardiovascular disease (5 papers); developmental delay (4); Dystonia (4); pneumococcal infection (4); idiopathic pulmonary fibrosis (3); immune dysfunction (3); metabolic disorder (3); neurological disease (3); adrenocortical carcinoma (2); allergic reactions (2); Arthritis (2); autism (2); bacterial pneumonia (2); breast carcinoma (2); diabetes (2); esophageal squamous cell carcinoma (2); gastric cancer (2); heart failure (2); metabolic syndrome (2); pancreatic cancer (2); Parkinsonism (2); psychiatric disease (2); acrodermatitis enteropathica (1); acute lung injury (1); acute myeloid leukemia (1); adenocarcinoma (1); Allergy (1); Atrophy (1); bladder disease (1); blood pressure (1).
A further 73 diseases each share a sentence with SLC39A8 in 1 paper.